IFT52 (intraflagellar transport 52)
Description:
Involved in ciliogenesis as part of a complex involved in intraflagellar transport (IFT), the bi-directional movement of particles required for the assembly, maintenance and functioning of primary cilia. Required for the anterograde transport of IFT88.
Synonyms: C20orf9; NGD5; CGI-53; dJ1028D15.1; NGD2
Tractability: PROTAC: ubiquitination databases record sites on it.
Gene: Protein-coding gene on chromosome 20 (43,590,925 to 43,647,299, forward strand). Ensembl gene ENSG00000101052.
Subcellular location: Cell projection, cilium
Subcellular location (Human Protein Atlas): Microtubules; Basal body; Cytosol; Primary cilium
Pathways (Reactome):
Organelle biogenesis and maintenance: Intraflagellar transport
Signal Transduction: Hedgehog 'off' state
Gene Ontology:
Molecular function: protein binding
Biological process: cilium assembly; intraciliary anterograde transport; intraciliary transport
Cellular component: ciliary base; intraciliary transport particle A; intraciliary transport particle B; photoreceptor connecting cilium; centriole; ciliary tip; cilium; motile cilium; centrosome; ciliary basal body; dendrite terminus; photoreceptor cell cilium
Genetic constraint (gnomAD): Loss-of-function variants: 25 observed, 31.29 expected, observed/expected ratio (o/e) 0.8, 90% interval 0.58 to 1.12. The upper end of that interval is the gene's LOEUF score, 1.12, which puts it in group 4 of 6, group 1 being the genes least tolerant of losing a copy. Missense variants: 278 observed, 334.16 expected, observed/expected ratio (o/e) 0.83, 90% interval 0.75 to 0.92. Synonymous variants: 127 observed, 127.65 expected, observed/expected ratio (o/e) 0.99, 90% interval 0.86 to 1.15.
Gene-disease validity (ClinGen):
ClinGen rates the evidence that IFT52 causes each of these diseases.
short-rib thoracic dysplasia 16 with or without polydactyly (autosomal recessive): Moderate.
Homologues: Orthologues: chimpanzee IFT52 (100% identical), macaque IFT52 (99% identical), dog IFT52 (94% identical), rabbit IFT52 (93% identical), pig IFT52 (93% identical), mouse Ift52 (89% identical), rat Ift52 (89% identical), guinea pig IFT52 (86% identical), zebrafish ift52 (77% identical), Caenorhabditis elegans osm-6 (38% identical), Drosophila melanogaster IFT52 (35% identical).
Diseases named in the same sentence as IFT52 in open-access papers:
IFT52 is named in the same sentence as 10 diseases in open-access papers, as found by Europe PMC text mining. Sharing a sentence is not in itself a finding about the gene and the disease. The quoted sentences say what the papers report.
retinal degeneration (2 papers, 2022 to 2025). Degeneration of the retina. "A variety of genes involved in IFT, such as Ift88, Ift122, Ift81, Ift172, and Ift52, have been reported to be associated with retinal degeneration." (PMID 36171205, 2022). "Similarly, mutations in IFT52/OSM-6 result in shortening of cilia and retinal degeneration in humans." (PMID 41278837, 2025).
breast carcinoma (1 paper, 2021). "However, the expression of IFT52 and IFT81 was upregulated in the breast cancer cells, and the expression of IFT88 showed an undetectable difference between HBL-100 and MCF-7 cells." (PMID 33748116, 2021).
retinal ciliopathies (1 paper, 2022). "IFT52 has been linked to short-rib thoracic dysplasia and retinal ciliopathies." (PMID 35076015, 2022).
short rib-polydactyly syndrome (1 paper, 2025). Short rib-polydactyly syndromes are a group of bone malformations characterized by a narrow thorax and polydactyly (usually preaxial). "IFT52 is a core protein of IFT‐B1b that interacts with IFT88, which plays a vital role in cilium assembly, and its mutation can induce cilium disruption and result in short rib polydactyly syndrome." (PMID 39915276, 2025).
cancer (2 papers, 2016 to 2020). A tumor composed of atypical neoplastic, often pleomorphic cells that invade other tissues. "We also found GIST to highly express four genes (KIF3A, IFT52, IFT88, and IFT172), which are associated with PC function in several cancers." (PMID 27793025, 2016). "Finally, we demonstrate the importance of IFT88 and IFT52 for efficient centrosome clustering in cancer cell lines naturally harboring supernumerary centrosomes and the importance of IFT88 for cancer cell proliferation." (PMID 32270908, 2020).
IFT52 also shares sentences with these, for which no sentence is quoted: ciliopathy (1 paper); fibrosis (1); Jeune syndrome (1); orofaciodigital syndrome (1); Senior-Loken syndrome (1).